MTOR (mechanistic target of rapamycin kinase)
Diseases named in the same sentence as MTOR in open-access papers (continued):
Sharing a sentence is not in itself a finding about the gene and the disease.
hepatocellular carcinoma (continued). "Conversely, it was found that upon inhibition of mTOR in macrophages in hepatocellular carcinoma (HCC), STAT3 decreased the secretion of both IL-10 and IL-12 and inhibited angiogenesis in vivo." (PMID 39003350, 2024). "This phosphorylation event was observed in rat hepatoma cells, where a connection between the mTOR pathway and the phosphorylation of IRS-2 serine residues, specifically Ser907 and Ser675, was es-tablished." (PMID 38248343, 2024). "In another study, SNAT1 regulated the development of hepatocellular carcinoma by modulating phosphatidylinositol 3-kinase (PI3K)/protein kinase B (AKT)/mammalian target of rapamycin (mTOR) signaling via glutamine-mediated energy metabolism." (PMID 39273030, 2024). "Studies have shown that EVs can deliver miR-199a to target the mTOR pathway, inhibiting mTOR activation and subsequent phosphorylation of 4EBP1 and 70S6K in hepatocellular carcinoma (HCC) cells, thus restoring doxorubicin sensitivity in HCC cells." (PMID 39802949, 2024). "Inhibition of the PI3K/Akt/mTOR pathway can induce apoptosis and autophagy in hepatocellular carcinoma cells." (PMID 39247820, 2024). "Recent studies have reported that GS can promote the malignant phenotype of hepatocellular carcinoma by activating mTOR signaling pathway." (PMID 38811958, 2024). "For instance, FSTL1 can bind to TLR4, activating AKT/mTOR/4EBP1 signaling and enhancing hepatocellular carcinoma metastasis and stemness." (PMID 38605354, 2024). "In this respect, Bi and co-workers exhibited that via PI3K/AKT/mTOR, miR-210 enhances hepatocellular carcinoma progression by regulating macrophage autophagy." (PMID 39315094, 2024). "KEGG enrichment analysis highlighted the primary enrichment of DEGs in signaling pathways involving autophagy, mTOR, and hepatocellular carcinoma, among others." (PMID 38317842, 2024). "PESV can regulate PI3K/AKT/mTOR pathway by inducing autophagy of hepatocellular carcinoma cells to play an antitumor role." (PMID 38622523, 2024). "The antiproliferative characteristics of mTOR-inhibitors have been shown to improve survival following transplantation in adult hepatocellular carcinoma patients." (PMID 38473259, 2024). "HBV infection results in the excessive accumulation of bile acids and sphingolipids in the serum, leading to the activation of the MAPK/mTOR pathway in HBV+ hepatoma cells and subsequent reprogramming of lipid metabolism in hepatocellular carcinoma." (PMID 38773448, 2024). "Sarmentosin induces autophagy and apoptosis in hepatocellular carcinoma cells through Nrf2 activation and mTOR inhibition, effectively suppressing tumor growth in vivo." (PMID 39315094, 2024). "PSD not only induced apoptosis, but also inhibited cell growth and angiogenesis, through modulation of the PI3K/Akt/mTOR pathway in human hepatocellular carcinoma." (PMID 38200409, 2024). "Treatment of the human hepatoma cell line, HepG2, with capsaicin, resulted in suppression of the protein kinase B (Akt)/mammalian target of the rapamycin (mTOR) pathway and upregulation of PPAR-g protein expression." (PMID 38474385, 2024). "Rapamycin, on the other hand, exerts its antineoplastic effects on hepatic carcinoma cells by suppressing the mTOR signaling pathway, thereby influencing cell proliferation, growth, and metabolism." (PMID 38967628, 2024). "Observations have also shown that vascular morphological alterations through intussusceptive angiogenesis occur in hepatocellular carcinoma models during treatment with sirolimus, an inhibitor of the mammalian target of rapamycin (mTOR) pathway." (PMID 38590656, 2024). "This indicates that G-CSF promotes the expansion of hepatocellular carcinoma cells and their angiogenic capabilities by repressing SHP2 function within the tumor-associated macrophages, which in turn triggers the PI3K/AKT/mTOR signaling pathway." (PMID 38967628, 2024).
hepatocellular carcinoma (continued). "Third, it is predicted to be the potential microRNAs that target the 3’UTR of mTOR mRNA with online bioinformatics methods, and were verified on endothelial cells, hepatocellular carcinoma." (PMID 37736726, 2023). "The results of KEGG assays indicated that the 40 differential expressed FRGs were mainly enriched in the longevity regulating pathway, AMPK signaling pathway, the mTOR signaling pathway, and hepatocellular carcinoma." (PMID 36873737, 2023). "KEGG enrichment analysis of these 183 and 95 genes indicated that the MAPK, PI3K-AKT, JAK-STAT, hepatocellular carcinoma, and mTOR signaling pathways were the common pathways regulated by the YTHDC1-GLUT3 axis." (PMID 37258572, 2023). "The mechanistic target of rapamycin (mTOR) is considered the central node of a network involved in NAFLD and NAFLD-associated hepatocellular carcinoma development." (PMID 37047048, 2023). "Reduction of mTOR phosphorylation was also shown in Huh7 cells, a human hepatoma cell line, which were knocked down by GPR180 shRNA." (PMID 36726016, 2023). "We found that ZYX was significantly upregulated in the HCC tissues compared to the normal liver tissues, and enhanced the malignant potential of hepatoma cells by activating the oncogenic AKT/mTOR signaling pathway." (PMID 37547758, 2023). "It has been reported that coptisine chloride possesses anti-cancer activity through the inhibition of PI3K/Akt/mTOR signaling and subsequent mitochondrial ROS production in the hepatocellular cancer Hep3B cells." (PMID 36859380, 2023). "A previous study has determined that CD147 reprograms fatty acid metabolism via regulating Akt/mTOR/SREBP1c and P38/PPARα pathways, which is related to the proliferation and metastasis of hepatocellular carcinoma cells." (PMID 37880644, 2023). "Recent studies have shown that the mTOR-related signaling system can either promote or inhibit ferroptosis in hepatocellular carcinoma cells." (PMID 38274225, 2023). "13-Acetoxysarcocrassolide also reduced cellular viability with features of apoptosis (5 μM, 24 h) in HA22T and HepG2 hepatocellular carcinoma cells, associated with reduced p-PI3K, p-AKT, p-mTOR, and p-p70S6K proteins." (PMID 38132936, 2023). "Using a subcutaneous tumor formation model in nude mice, we observed that miR-21-5p inhibits the ferroptosis of hepatoma cells by regulating the AKT/mTOR signaling pathway through MELK in vivo." (PMID 37008632, 2023). "Inhibition of PI3K/Akt/mTOR signaling by apigenin and chrysoeriol induces apoptosis and autophagy in hepatocellular carcinoma cells." (PMID 36817123, 2023). "Previous studies showed that knockdown of SIRT6 can inhibit MAPK/ERK and PI3K/AKT/mTOR signaling pathways in hepatocellular carcinoma and diffuse large B-cell lymphoma." (PMID 37542062, 2023). "In summary, we basically concluded that S100A10 was involved in the growth process of hepatocellular carcinoma through the ANXA2/Akt/mTOR signaling pathway." (PMID 37420211, 2023). "Previous studies have revealed that chronic myeloid leukaemia and hepatocellular carcinoma display enhanced production of BCAAs, which promote mTOR activation." (PMID 37076565, 2023). "In one study, miR-873 activated the key glycolytic proteins AKT/mTOR via targeting NDFIP1 to promote hepatocellular carcinoma growth and metastasis." (PMID 36929005, 2023). "For example, linalool, a plant-derived monoterpene, induces G0/G1 arrest and apoptosis in hepatocellular carcinoma HepG2 cells through Ras, MAPKs, Akt/mTOR signaling pathways." (PMID 36923503, 2023). "6-shogaol combined with 5-fluorouracil (5-FU) triggers apoptosis and cell cycle arrest in hepatocellular carcinoma cells by inhibiting AKT/mTOR/MRP-1 signaling." (PMID 37875983, 2023). "Alamo reported on 32 patients with malignancy (50% hepatocellular carcinoma) after liver transplantation switched to an mTOR inhibitor as CNI-free therapy." (PMID 37200246, 2023).
hepatocellular carcinoma (continued). "Isoviolanthin extracted from Dendrobium officinale leaves targets the TGF-β/Smad and PI3K/AKT/mTOR pathways to suppress TGF-β1-induced EMT in hepatocellular carcinoma (HCC) cells." (PMID 38026996, 2023). "For example, S100A10 promotes hepatocellular carcinoma, gastric cancer, and osteosarcoma cell proliferation and suppresses apoptosis via enhanced aerobic glycolysis through mTOR signaling." (PMID 37892132, 2023). "In hepatocellular carcinoma cells, SphK1 inhibition by cinobufotalin induced ceramide production and Akt-mTOR inhibition." (PMID 37604912, 2023). "The findings demonstrated that MELK stimulated the expression of DLAT in hepatocellular carcinoma (HCC) cells through the activation of the PI3K/mTOR signaling pathway." (PMID 37949877, 2023). "NAP1L5 inhibits tumor growth and metastasis by inhibiting the PI3K/Akt/mTOR signaling pathway and myosin heavy chain 9 in hepatocellular carcinoma." (PMID 37667226, 2023). "The PI3K/Akt/mTOR pathway has been reported to be overexpressed in nearly 50% of hepatocellular carcinomas, and it plays a crucial role in tumorigenesis and progression." (PMID 37587524, 2023). "SLC7A6 is upregulated in hepatocellular carcinoma, leading to a significant increase in the uptake of amino acids, which further activates the mTOR signaling cascade and promotes tumor formation." (PMID 37940982, 2023). "IGF2BP3 was previously demonstrated to be an upstream regulator of AKT/mTOR signalling in hepatocellular carcinoma." (PMID 34894048, 2022). "In hepatocellular carcinoma, miRNA-223 inhibited tumorigenesis and promoted apoptosis through the mTOR signaling pathway in vitro." (PMID 36244127, 2022). "In addition to its replication stress checkpoint functions, SLFN11 interacts with ribosomal protein S4 X-linked (RPS4X) and suppresses the mTOR signaling pathway in hepatocellular carcinoma (HCC), inhibiting HCC growth and metastasis." (PMID 35768579, 2022). "A previous study showed an inhibitory effect of PA on cell proliferation, invasiveness, and tumour growth by affecting the membrane parameters, dysregulating energy metabolism, and influencing mTOR pathway phosphorylation in hepatocellular cancer." (PMID 35735113, 2022). "In conclusion, our findings reveal that USF2-mediated upregulation of TXNRD1 contributes to hepatocellular carcinoma progression by activating Akt/mTOR signaling." (PMID 36319631, 2022). "SPAG5 is a mitotic spindle protein, which promotes cancer cell proliferation and invasion by activating AKT/mTOR pathway in bladder and hepatocellular cancer." (PMID 36304306, 2022). "Rapamycin inhibits the phosphorylation of mTOR in vitro and in vivo, which effectively inhibits the growth and proliferation of hepatocellular carcinoma cells." (PMID 36374212, 2022). "Autophagy inhibitor CQ or mTOR agonist can partially weaken the auxo-action of SSd to radiation-induced hepatoma cell death." (PMID 36499429, 2022). "This evidence suggests that the activation of the PI3K/Akt/mTOR signaling pathway is involved in the progression of hepatocellular carcinoma." (PMID 36374212, 2022). "For example, HAGLROS promotes proliferation, inhibits apoptosis and enhances autophagy by regulating the miR-5095/ATG12 axis and PI3K/AKT/mTOR signalling pathway in hepatocellular carcinoma." (PMID 35664787, 2022). "The dysregulated PI3K/AKT/mTOR pathway acts as the main regulator of tumorigenesis in hepatocellular carcinoma (HCC)." (PMID 35592706, 2022). "And miR-199a-modified ASC-Exos improved hepatocellular carcinoma chemosensitivity via targeting mTOR signaling." (PMID 36572886, 2022). "The PI3K/Akt/mTOR signaling pathway is overexpressed in nearly 50% of hepatocellular carcinoma cases, and its abnormal activation affects cell proliferation, metabolism, tumor cell differentiation, lipid metabolism, autophagy and EMT." (PMID 36374212, 2022).
hepatocellular carcinoma (continued). "The other one patient was receiving mTOR inhibitor only (CNI treatment was discontinued six months before renal biopsy due to hepatocellular carcinoma relapse)." (PMID 36180855, 2022). "In summary, we provide novel evidence that USF2-mediated upregulation of TXNRD1 contributes to hepatocellular carcinoma progression by activating Akt/mTOR signaling." (PMID 36319631, 2022). "Immunosuppressive medication with so-called mTOR inhibitors seems to have a tumor-suppressive effect, as improved survival has been shown under this medication for patients with recurrent hepatocellular carcinoma after liver transplantation." (PMID 35740555, 2022). "Interference of YAP considerably reinforced autophagic flux by cumulating RAC1-driven ROS, which result in deactivation of mTOR in hepatocellular carcinoma cells." (PMID 35725558, 2022). "We aimed to characterize the roles of small GTPase activators of mTOR including RagC, Rab1A, Rab5, and Arf1 in senescence-like hepatoma cell line HepG2." (PMID 36267578, 2022). "The PI3K/AKT/mTOR pathway plays crucial roles in the proliferation, differentiation and invasion of hepatoma cells." (PMID 35836300, 2022). "Overall, exogenous H2S ameliorated hepatocellular carcinoma through promoting autophagy by inhibiting PI3K/AKT/mTOR pathway." (PMID 35409395, 2022). "Consistent with our previous results, the levels of the phosphorylated Akt and mTOR were increased under the high glucose condition but decreased in hepatoma cells in the presence of IFNα-2a in hepatoma cells." (PMID 35186790, 2022). "Previous studies have demonstrated that TGF-β induced epithelial to mesenchymal transition (EMT) in hepatocellular carcinoma (HCC) through the PI3K/Akt/mTOR signalling pathways." (PMID 35273654, 2022). "The TCRP1 protein degradation pathway in hepatocellular carcinoma (HCC) cells results in the suppression of the AKT/mTOR signaling pathway and an increase in autophagic flux." (PMID 36358919, 2022). "For example, LncRNA HOTAIR induced GLUT1 expression via activating the mTOR pathway, promoting cell proliferation in hepatocellular carcinoma cells and tissues." (PMID 36072431, 2022). "The effects of crosstalk between mTOR and its upstream regulators, Notch, Hedgehog, and Hippo, on the occurrence and development of NAFLD-associated hepatocellular carcinoma are also summarized." (PMID 36012464, 2022). "For example, ST3GAL6 overexpression is required for multiple myeloma cell homing to bone marrow niche and subsequent tumor growth, while ST3GAL6 can induce AKT/mTOR signaling to promote hepatocellular carcinoma cell proliferation and invasion." (PMID 36092699, 2022). "At present, there are many studies on the crosstalk between mTOR and novel pathways in cancers such as gastric cancer and esophageal cancer, while there are few studies on the influence of hepatocellular carcinoma." (PMID 36012464, 2022). "Apigenin inhibits the expression of high‐risk genes and acts as an anticancer agent to induce apoptosis in hepatocellular carcinoma cells by inhibiting the P13K/Akt/mTOR pathway." (PMID 35293027, 2022). "In previous studies, it was reported that miR‐100‐5p inhibited the activity of mTOR and facilitated the autophagy of hepatocellular carcinoma cells." (PMID 35411593, 2022). "OSGIN1 was regulated by long non-coding RNA (lnRNA) UCA1 to mitigate autophagy flux-mediated apoptosis through the mTOR pathway in human hepatocellular carcinoma cells (HepG2) under arsenic toxicity." (PMID 35625730, 2022). "Inhibition of the Akt/mTOR pathway reduced viability and glycolysis in hepatocellular carcinoma cells." (PMID 35903069, 2022). "The results elucidated that lycorine promoted apoptosis and autophagy through suppressing TCRP1/AKT/mTOR pathway in Hepatocellular carcinoma." (PMID 35459265, 2022).
hepatocellular carcinoma (continued). "In the SMD simulation, compounds 1 and 2 were predicted to be very promising inhibitors against PI3K/mTOR and direct their cytotoxic activity against Hepatocellular carcinoma." (PMID 36558112, 2022). "As reported, apigenin induces apoptosis and autophagy by inhibiting the PI3K/Akt/mTOR pathway in hepatocellular carcinoma cells." (PMID 35965686, 2022). "In our previously research, U12, a UDCA derivative, was found to show anti-hepatoma activities via mTOR/S6K1, cyclinD1/CDK2/4 and caspase-dependent apoptotic signaling pathways in hepatocellular carcinoma cells." (PMID 35056164, 2022). "Another study revealed that miR-100 promotes the autophagy of hepatocellular carcinoma cells by inhibiting the expression of the mTOR pathway." (PMID 34976182, 2022). "A previous report has demonstrated that arenobufagin induces apoptosis and autophagy via inhibition of the PI3K/Akt/mTOR pathway in human hepatocellular carcinoma cells." (PMID 36235115, 2022). "In the mechanistic study, we found that NAP1L5 affects the occurrence and development of hepatocellular carcinoma by regulating MYH9 to inhibit the PI3K/AKT/mTOR signaling pathway." (PMID 36374212, 2022). "One patient received an mTOR inhibitor only (CNI treatment was discontinued six months before the renal biopsy due to hepatocellular carcinoma relapse)." (PMID 36180855, 2022). "In the same study, the activity of both mTOR complexes was significantly induced following the exposure of the human hepatoma cell line (HepG2) to 1 μM BDE-47." (PMID 36430706, 2022). "Our results are in line with observations in CD133-expressing cancer cells, liver cancer cells and hepatocellular carcinoma cells, showing that inhibition of the mTOR pathway resulted in increased cancer cell stemness." (PMID 35406578, 2022). "Taken together, IFNα-2a inhibits Akt/mTOR activation and enhances autophagy independently on glucose concentrations in hepatoma cells." (PMID 35186790, 2022). "SOCS5 inhibition induces autophagy to impair metastasis in hepatocellular carcinoma cells via the PI3K/Akt/mTOR pathway." (PMID 34128694, 2021). "Our data indicate that deletion of ChREBP delays insulin-induced hepatocarcinogenesis, suggesting a combined oncogenic and lipogenic function of ChREBP along AKT/mTOR-mediated proliferation of hepatocytes and induction of hepatocellular carcinoma." (PMID 34685767, 2021). "We have next investigated the signaling pathway involved in macrophage autophagy inhibition by hepatoma cells and first focused on mTOR which is a key factor that controls autophagy." (PMID 34552122, 2021). "Accumulating evidence has revealed that MALAT1 enhances the expression of serine arginine-rich splicing factor 1 (SRSF1) and activates the mammalian target of rapamycin (mTOR) signaling pathway in hepatocellular carcinoma (HCC)." (PMID 34001131, 2021). "In hepatocellular carcinoma, mTOR blockade not only hindered PI3K/AKT/mTOR signal but also reduced the concentration and stability of FBP1/2, thus restraining the proliferation of hepatocellular carcinoma cells." (PMID 34568005, 2021). "It has also been reported that it promotes the proliferation and migration of hepatocellular carcinoma by regulating the AMPK/mTOR/S6K1 signaling pathway." (PMID 34589110, 2021). "The mechanism underlying the anti-tumor effects of apigenin in hepatocellular carcinoma HepG2 cells is related to the induction of apoptosis and autophagy through the inhibition of the PI3K/AKT/mTOR pathway." (PMID 34575981, 2021). "Previous studies indicated that the anti-cancer effects of AB4 was correlated with the inhibition of PI3K/Akt/mTOR pathway in hepatocellular carcinoma." (PMID 34890366, 2021). "Our results preliminarily showed that SSd can increase the radiosensitivity of hepatoma cells, which is related to the inhibition of mTOR phosphorylation by SSd and the promotion of autophagy in hepatoma cells." (PMID 33628104, 2021).